SSBP3 (single stranded DNA binding protein 3)
Description:
May be involved in transcription regulation of the alpha 2(I) collagen gene where it binds to the single-stranded polypyrimidine sequences in the promoter region.
Synonyms: SSDP; SSDP1; CSDP; FLJ10355
Tractability: PROTAC: ubiquitination databases record sites on it; its protein half-life has been measured.
Gene: Protein-coding gene on chromosome 1 (54,225,432 to 54,413,479, reverse strand). Ensembl gene ENSG00000157216.
Subcellular location: Nucleus
Subcellular location (Human Protein Atlas): Nucleoplasm
Gene Ontology:
Molecular function: protein binding; transcription coactivator activity; single-stranded DNA binding
Biological process: positive regulation of transcription by RNA polymerase II; head development; head morphogenesis; midbrain-hindbrain boundary initiation; positive regulation of anterior head development; positive regulation of cell population proliferation; positive regulation of DNA-templated transcription; prechordal plate formation; protein-containing complex assembly
Cellular component: nucleus; protein-containing complex; transcription regulator complex
Genetic constraint (gnomAD): Loss-of-function variants: 5 observed, 60.18 expected, observed/expected ratio (o/e) 0.0831, 90% interval 0.042 to 0.17. The upper end of that interval is the gene's LOEUF score, 0.17, which puts it in group 1 of 6, group 1 being the genes least tolerant of losing a copy. Missense variants: 312 observed, 487.77 expected, observed/expected ratio (o/e) 0.64, 90% interval 0.58 to 0.7. Synonymous variants: 196 observed, 178.28 expected, observed/expected ratio (o/e) 1.1, 90% interval 0.98 to 1.24.
Homologues: Orthologues: mouse Ssbp3 (100% identical), pig SSBP3 (100% identical), guinea pig SSBP3 (97% identical), rabbit SSBP3 (97% identical), rat Ssbp3 (93% identical), tropical clawed frog ssbp3 (92% identical), zebrafish ssbp3a (85% identical), macaque SSBP3 (75% identical), zebrafish ssbp3b (75% identical), Drosophila melanogaster Ssdp (62% identical), Caenorhabditis elegans sam-10 (38% identical), Caenorhabditis elegans Y53F4B.5 (13% identical). Paralogues in human: SSBP2 (78% identical), SSBP4 (73% identical).
Diseases named in the same sentence as SSBP3 in open-access papers:
SSBP3 is named in the same sentence as 13 diseases in open-access papers, as found by Europe PMC text mining. Sharing a sentence is not in itself a finding about the gene and the disease. The quoted sentences say what the papers report.
autism (1 paper, 2023). Persistent deficits in social interaction and communication and interaction as well as a markedly restricted repertoire of activity and interest as well as repetitive patterns of behavior. "As the characteristics of Drosophila Ssdp- and human SSBP3-expressing neurons are very similar, we next asked whether manipulating neuronal activity using optogenetic actuators of Ssdp-labeled neurons would also alter autism-associated behaviors." (PMID 37486945, 2023). "Interestingly, SSBP3 expression in human brain, colocalizes with SLC17A7, a gene from the solute carrier family that has been associated with autism, suggesting a potential link between Ssdp and autism-related pathways." (PMID 37486945, 2023). "Out of these 6 autism-related genes, only 3 (CPT2, SCP2 and SSBP3) have strong orthologs in flies (DIOPT Score >0.5), with the highest orthology for SSBP3 (DIOPT Score = 0.93)." (PMID 37486945, 2023).
Epileptic encephalopathy (1 paper, 2023). A condition in which epileptiform abnormalities are believed to contribute to the progressive disturbance in cerebral function. "One of the identified networks, M3, consists of 150 genes that also includes SSBP3, and M3 was found to be enriched for mutations in patients with ID and epileptic encephalopathy." (PMID 37486945, 2023).
teratoma (1 paper, 2016). A non-seminomatous germ cell tumor characterized by the presence of various tissues which correspond to the different germinal layers (endoderm, mesoderm, and ectoderm). "The trophoblast-like phenotype induced by Ssbp3 was also evaluated by teratoma formation and early embryo injection assays." (PMID 27236334, 2016). "Of note, Ssbp3-overexpressing ESC-produced teratomas contained obvious hemorrhage." (PMID 27236334, 2016). "Furthermore, overexpression of Ssbp3 reduced the methylation level of the Elf5 promoter and promoted the generation of teratomas with internal hemorrhage, indicative of the presence of trophoblast cells." (PMID 27236334, 2016).
tumor (2 papers, 2016 to 2022). "Here, we implicate two LDB1-binding proteins, single-stranded binding protein 2 (SSBP2) and 3 (SSBP3), in controlling LMO4 and LDB1 protein abundance in HNSCC and in regulating specific tumor cell functions in this disease." (PMID 27780223, 2016).
SSBP3 also shares sentences with these, for which no sentence is quoted: cancer (3 papers); Atrophy (1); benign colon neoplasm (1); carcinoma of the (1); colon adenocarcinoma (1); esophageal carcinoma (1); glioblastoma multiforme (1); neurodevelopmental disorder (1); open-angle glaucoma (1).